NOTCH1 (notch receptor 1)
Diseases named in the same sentence as NOTCH1 in open-access papers (continued):
Sharing a sentence is not in itself a finding about the gene and the disease.
tumor (continued). "In the present study, GC evolution induced elevations of Notch1 and Notch2 in both peripheral bloods and tumor tissues, indicating that Notch signaling might take part in GC progression." (PMID 30988066, 2019). "IHC analysis of the primary tumor tissues showed that estrogen promoted the expression of CD49f, ERα, NOTCH1, and Vimentin, and that the expression of E-cadherin was decreased; the changes induced by E2 were significantly inhibited by tamoxifen, and the Western blot results showed the same trends." (PMID 31122254, 2019). "To investigate the hierarchy between these different tumour cell populations, marked by Notch1 or Lgr5 expression, we used the R26mTmG double fluorescent line, allowing us to distinguish between initially labelled cells (that we called “Mothers”) and their derived progeny." (PMID 30696875, 2019). "Moreover, Notch1 was up-regulated in the tumor cells at the mRNA and protein levels and was activated at the protein level in the tumor cells by TNFα stimulation." (PMID 31105691, 2019). "Moreover, in the absence of TNFα stimulation, basal p65 activation mainly in the tumor cells has induced Notch1 activation (Figures 9A1,C1), which then contributed to a contact-dependent induction of CXCL8." (PMID 31105691, 2019). "However, to date, our study provides the first mechanistic information on the regulation of CXCL8 by Notch1 in the tumor-stroma-inflammation network." (PMID 31105691, 2019). "In ESCC, NOTCH1 plays a tumor-suppressive role during ESCC development." (PMID 31289612, 2019). "Moreover, since Notch1 activation following TNFα stimulation depended almost entirely on p65 activation, it is highly possible that Notch-mediated regulation of tumor cell migration and invasion was also induced by p65 activation, as result of TNFα activation." (PMID 31105691, 2019). "Although Atoh-1 has been shown to function as a tumor suppressor, patients with mucinous colorectal tumors exhibit high levels of Atoh-1 expression and retain prominent secretory cell components possibly due to the absence or inactivation of Notch-1 signaling." (PMID 30323897, 2018). "It is worth noting that Notch1 could be an oncogene or a tumour suppressor in context dependent manner." (PMID 30544959, 2018). "Additionally, decreased expression of Wnt target genes via a tumor suppressive effect of Notch-1 has been described in human CRC." (PMID 30323897, 2018). "CD8+ T cell depletion significantly compromised the effect of Notch1 expression on tumor growth." (PMID 29301578, 2018). "Kitajewski’s group showed that in mammary gland tumor murine model, in which Jagged1 tumor expression was upregulated by ectopic expression of FGF4, Notch inhibition through Notch1 decoy disrupted tumor angiogenesis and delayed the growth of murine Mm5MT xenografts." (PMID 30154786, 2018). "Furthermore, NICD1 expression, the active form of NOTCH1, was fivefold to tenfold higher in tumor cells from spinal metastases compared with cells from primary tumor sites." (PMID 30297829, 2018). "In contrast, Notch1 immunolabeling could be easily observed in cells surrounding the tumor nodules, similar to that of CD34, which marks endothelial cells (ECs)." (PMID 29545603, 2018). "Both HMGA1 and NOTCH1 can act as oncogenes or tumour suppressors in a context-dependent manner." (PMID 29743479, 2018). "The relationship between these two prominent tumour-associated genes, HMGA1 and NOTCH1, may also have prognostic value in vivo." (PMID 29743479, 2018). "Our VN-/- murine model, where there is deletion of Notch-1 in intestinal epithelial cells, recapitulates the histological changes seen in human serrated adenomas and therefore gives us further insight into this neoplasia pathway." (PMID 30323897, 2018). "Furthermore, the Notch1 target gene Hes1 was expressed in tumor cells adjacent to CD31-expressing endothelial cells (ECs)." (PMID 29410396, 2018). "In this context, activated NOTCH1 signaling promotes tumor growth." (PMID 30158530, 2018).
tumor (continued). "Accumulating evidence reveals that Notch1 is an important factor in tumour progression." (PMID 30170559, 2018). "Notch-1 was found to play an important role in numerous neoplasms." (PMID 30323897, 2018). "Significantly higher NOTCH1 mRNA expression was found in p16-positive tumor probes." (PMID 29533972, 2018). "In support of this idea, DAOY-NERT2HIF2α−/− cells exhibited higher HIF1α protein levels under hypoxic conditions and treatment of the DAOY-NERT2HIF2α−/− cells with the HIF1α inhibitor KC7F2 reduced tumor growth both under control and Notch1 ICD-activated conditions." (PMID 29993038, 2018). "The miR data bases, TargetScan and miRNATar Base were used to predict the target genes of miR-3178 that may regulate tumor growth and metastasis, and Notch1 was recognized as a potential target." (PMID 30333478, 2018). "Intriguingly, IHC revealed that Notch1 is predominantly expressed in the tumor microenvironment." (PMID 29545603, 2018). "miR-3178/p-Notch1 partly neutralized the inhibitory effects of miR-3178 on tumor volume." (PMID 30333478, 2018). "Thus, inhibition of Notch1 can be tumor suppressive by removing the inhibition on E-cadherin expression, regardless of hypoxia." (PMID 30515368, 2018). "Notch1-activating agents have been proposed earlier, and based on our results this may be considered together with targeting macrophages in the tumor." (PMID 30283446, 2018). "It has been suggested that Notch1 may play a particularly important role in GICs, a sub-population of tumor cells that have stem-like properties." (PMID 29410396, 2018). "The results suggested that Notch1 might promote tumor growth in vivo via suppression of antitumor immunity." (PMID 29301578, 2018). "The relationship between disordered NOTCH1 and tumor development has been hotly debated." (PMID 29665790, 2018). "For Notch1, the protein in the Notch signaling pathway, it was also involved in tumor progression." (PMID 30001383, 2018). "Many tumor-suppressive miRNAs have also been identified with NOTCH1-sensitized T-ALL mouse model." (PMID 29435192, 2018). "Furthermore, they exert anti-inflammatory effects and modulate Wnt/β catenin, PI3K/Akt and Notch-1 key pathways for tumor initiation." (PMID 30487390, 2018). "Thus, the Notch1-Snail1 signaling pathway activation not only played a role in HCC tumor pathogenesis, but also contributed to sorafenib resistance." (PMID 30405889, 2018). "Furthermore, GSI-mediated anti-tumor effects resulted in targeting Notch1- and Snail1-mediated EMT and CSC stemness." (PMID 30405889, 2018). "Also at the protein levels, the cleaved, active form of Notch1 (NICD1) and Hes1, which is encoded by a Notch target gene, were decreased in Ap4-deficient tumor organoids indicating a decrease in Notch signaling." (PMID 30177706, 2018). "On the other hand, FBXW7 is a tumor suppressor and its inactivation could result in the constitutive activation of NOTCH1, cyclin E, c-Myc and other oncogenic factors." (PMID 29506494, 2018). "Tumor-derived miR-146a may induce the activation of Notch1 in BMSCs stimulating them to secrete CCL2 and several cytokines including IL-8, IL-6, CXCL1, IP-10, and CCL5 that enhance myeloma cell viability and migration." (PMID 30154786, 2018). "Studies suggest a tumor suppressive function for Notch1 in neuroendocrine lineage cells." (PMID 30004402, 2018). "These anti-tumor effects of miR-3178 were dependent on its direct regulation of Notch1." (PMID 30333478, 2018). "Notch1 is considered a tumor suppressor in HCC, but a bona fide oncogene in ICC." (PMID 29545603, 2018). "Activating mutations in NOTCH1 or loss of NUMB1, a negative regulator of NOTCH, occur in 10–30% of NSCLC patients, except in the squamous cell carcinoma subtype, where NOTCH mutations are usually inactivating and function as tumor suppressors." (PMID 30464927, 2018). "However, the compromised effect of CD4+ T cells or NK cells depletion was less important than CD8+ T cells in Notch1-mediated tumor growth." (PMID 29301578, 2018).
tumor (continued). "Accumulating evidence shows that Notch1 plays an important role in tumour progress." (PMID 30170559, 2018). "Our in vitro study indicated that the knockdown of Notch1 can inhibit tumor cell growth." (PMID 29410396, 2018). "Conditional expression of transgenic Notch1 intracellular domain (N1ICD) in activated antigen-specific CD8+ T cells induced cytotoxic responses and caused CD8+ T cells to become resistant to MDSC-mediated tolerogenic effects in tumor-bearing mice." (PMID 29915603, 2018). "The finding that c‐Jun plays a role in the transcription of Notch1 in both types of cancers where high Notch1 expression is either oncogenic or tumor suppressive suggests that the Notch1 induction pathway may be conserved." (PMID 28776955, 2017). "Notch1 signaling plays a key role in tumor progression of several human cancers, including CRC." (PMID 28035069, 2017). "Thus, we concluded that Dlx5 directly transactivates Notch1/3 genes and promotes β-selection escape, which eventually results in tumor formation." (PMID 28122332, 2017). "Moreover, we further demonstrated that LINC00152 executes tumor-promoting functions by sponging miR-139-5p and then modulating NOTCH1 in CRC." (PMID 29180678, 2017). "Also, NOTCH1 pathway signaling is hyperactive during K-Ras(+/LSLG12Vgeo);RERTn(ert/ert) mouse lung carcinogenesis and is required for tumor maintenance." (PMID 27980227, 2017). "Luteolin suppressed tumor growth and Notch1 signaling in vivo." (PMID 28241766, 2017). "Taken together, the current study supports a tumor-promoting role of Notch1 in SCC while also providing novel mechanistic insight into how the local tissue microenvironment may influence Notch-mediated cell fate determination." (PMID 29170450, 2017). "In accordance with the previous studies, SNPs in Notch1 occurred in multiple types of tumor, which could serve as predictive biomarkers for the susceptibility and survival." (PMID 28415716, 2017). "Our results showed that inhibiting Notch signaling in GBM xenografts reduced the hypoxic fraction and delayed tumor growth, which further supports crosstalk between Notch signaling and hypoxia and suggests a potential mechanism whereby Notch1 downregulation radiosensitizes GBM cells." (PMID 29152141, 2017). "Until recently, it was unclear whether NOTCH1 functions as an oncogene or a tumor suppressor in cancer." (PMID 28947978, 2017). "Thus, based on these results, the Notch1-mediated proliferation of stem cells stimulates tumor angiogenesis." (PMID 28881855, 2017). "Notch-1 has been shown the oncogenic or tumor suppressive character." (PMID 28977931, 2017). "As ectopic ICN1 expression in EN60 tumors enhanced robustly intratumoral CD44H cell content, we hypothesized that Notch1 contributes to tumor initiation via generation of CD44H cells that have mesenchymal properties." (PMID 29170450, 2017). "Identification of regulators of AP‐1/c‐Jun expression or specific downstream effects of Notch1 induction in individual cellular contexts may discern its oncogenic or tumor antiproliferative effects." (PMID 28776955, 2017). "From these two aspects, it could be well concluded that miR-34a inhibited tumor formation via downregulating Notch1." (PMID 29340051, 2017). "Activated form of Notch1 promotes xenograft tumor growth when expressed ectopically." (PMID 29170450, 2017). "To determine how Notch1 may influence tumor initiation by CD44L and CD44H cells, we performed serial transplantation experiments." (PMID 29170450, 2017). "Additionally, DNMAML1 alone or NOTCH1-directed short hairpin RNA (shRNA) suppressed tumor volume significantly." (PMID 29170450, 2017). "Two independent whole exome sequencing studies report NOTCH1 mutations in about 14% and 15% of HNSCC respectively, and these studies hypothesize that NOTCH1 functions as a tumor suppressor in HNSCC based on its mutational characteristics." (PMID 31093353, 2017).
tumor (continued). "Preliminary research has shown that Notch1 has a good application prospect as an anti-tumor target." (PMID 28950865, 2017). "Dlx5 knockdown resulted in reduced tumor cell viability/proliferation and an increased population of apoptotic sub-G1 cells due, in part, to down regulation of phospho-Akt and/or Notch1/3." (PMID 28122332, 2017). "These anti-tumor effects could be abrogated by the overexpression of the miR-34a target genes Snail1 and Notch1." (PMID 28145431, 2017). "Thus, we have shown that Vav1 can play a GTPase-independent, tumor-suppressor-like role that mediates Notch1 signaling in T cells." (PMID 29136506, 2017). "Resveratrol has been shown to activate Notch-1, the signaling of which prevents tumor cell growth." (PMID 28629161, 2017). "Further investigation is required to explore whether rottlerin exerts its anti-tumor activity via inhibition of Notch-1 in animal mouse model." (PMID 28977931, 2017). "Furthermore, western blot analysis demonstrated that expression of Notch1 protein was also significantly decreased in tumor tissues compared with that in normal liver tissues (p<0.001)." (PMID 28507277, 2017). "In turn, this promotes tumor growth and metastatic dissemination in vivo, potentially reflecting a general pro-tumorigenic role of miR-494-3p by simultaneously downregulating the PTEN tumor-suppressor and increasing NOTCH1 and PI3K-AKT-S6RP signaling in vitro and in vivo." (PMID 27980227, 2017). "In the era of personalized medicine, next‐generation sequencing of tumor biopsy samples can be used to verify that the Notch1 promoter region does not contain mutations that can hinder the action of HDACi." (PMID 28776955, 2017). "However, the function of Notch1 is an oncogene or a tumor suppressor depending on the type of tumor and cellular context." (PMID 28415716, 2017). "In conclusion, expression of Notch1 may be related to tumor size, metastasis and microvascular invasion." (PMID 29093570, 2017). "Notch1, Notch2 and Notch4 mRNA expression levels were similar in AtT20 cells and normal adult pituitaries whereas Notch3 mRNA expression was reduced in corticotrope tumor cells in relation to normal mouse pituitary cells." (PMID 28915655, 2017). "Additionally, Notch1 is an important regulator of cellular proliferation in cancer stem cells, a small subset of cancer cells known to promote the tumor microenvironment and drive tumorigenesis." (PMID 29152142, 2017). "Since Notch1 and Twist1 play an important role in EMT and tumor progression, we examined whether there is a correlation between Notch1 and Twist1 in EMT status." (PMID 28035069, 2017). "We now report that Notch1/3 expression and Akt signaling are activated throughout T cell development in Lck-Dlx5 mice, and that tumor formation is associated with further intensification of Notch and Akt signaling." (PMID 28122332, 2017). "We and Zhou reported abnormal accumulation of Notch1 in HCC compared to surrounding non tumor tissue raising the possibility that deregulation of Notch1 receptor may participate to HCC tumorigenesis and cancer progression." (PMID 27167202, 2016). "The data are consistent with the NOTCH1 function as a tumour suppressor gene in HNSCC occurrence." (PMID 27035284, 2016). "To better understand the putative tumor promoting role of Notch1 in these prostate samples, we crossed Notch1-induced or repressed genes in PC3 and/or LNCaP cells with the genes differentially expressed in tumors according to Notch1 levels in at least 3 independent datasets." (PMID 27384993, 2016). "NOTCH3(+)CAFs may promote sprouting of tumor endothelial cells by a molecular mechanism similar to that of the DLL4/NOTCH1 pathway and stabilize the newly formed tumor vessels through JAG1/NOTCH3 interactions between endothelial cells and CAFs." (PMID 27124156, 2016).
tumor (continued). "Consistent with amplification and over expression of Notch pathway components, Immunohistochemical analysis for activated NOTCH1 intracellular domain (NICD) in a set of 50 patients indicated strong immunoreactivity for active Notch signaling present in 40% tumor samples." (PMID 27391340, 2016). "It is known that high expression levels of Jagged1, Notch 1 and Notch2 correlate with tumor progression of myeloma;44 in this context, it has been recently proposed an activating role of Notch on IL-6 proliferating signals in the bone marrow niche, which results in an enhancement of tumor growth." (PMID 27929540, 2016). "Furthermore, by comparing several PCa datasets with a focus on Notch1 expression in tumor vs normal prostate tissue, we found that the majority of samples was expressing low Notch1 levels." (PMID 27384993, 2016). "In conclusion, our data shows miR‐124 as a tumour suppressor during GC progression, which also interacts with the Notch1 signalling pathway, thereby suggesting a miR‐124/Notch axis that may have potential therapeutic implications for GC." (PMID 26612211, 2016). "In sum, our data reveal that Notch1 signaling activity is inversely correlated with the tumor-regulating function of MSC-DF and highlight Notch1 signaling as a molecular switch to control the tumor-regulating function of stromal fibroblasts in determining tumorigenesis and metastasis." (PMID 27813493, 2016). "The function of NOTCH1 in ESCC was firstly identified as a tumor suppressor." (PMID 27938406, 2016). "Inhibition of tumor growth by CO correlated with induction of P-Erk1/2 and cleavage of Notch1." (PMID 26993595, 2016). "NOTCH1 is regarded as a tumour suppressor in HNSCC because these missense SMs within the domain frequently harboured potential protein inactivation or were located in domains that affected the conserved residues in the NOTCH1 gene." (PMID 27035284, 2016). "In mice treated with the Notch1 blocking antibody there was a significant reduction in the percent of cells that were leaving the photo-converted regions of the tumor, indicating these tumor cells were less efficient at leaving the primary tumor." (PMID 27901093, 2016). "However, there are still considerable evidences questioning the tumor suppressor role of NOTCH1 in HNSCC." (PMID 27228302, 2016). "However, permanent down-modulation of the Notch pathway is also likely to be required for tumor development, as decreased Notch1 expression has been found also at late stages of cancer progression." (PMID 27384993, 2016). "Finally, the use of a Notch1 decoy was also shown to affect angiogenesis and reduce tumor growth via inhibition of Notch receptor activation." (PMID 26934331, 2016). "Therefore, the data indicate that Notch1 signaling serves as a molecular switch that determines the tumor-regulating function of MSC-DF." (PMID 27813493, 2016). "Moreover, the number of tumor-spheres for NOTCH1 blockade showed significant decrease compared with the control group, regardless of size distribution." (PMID 27108536, 2016). "For example, Notch1 PEST domain alterations are weak, and are only functional in the presence of Notch ligands, whereas the tumor-inducing potential of Notch1 HD domain mutations is higher, relying on both ligand hypersensitivity and ligand independent activation mechanisms." (PMID 26934331, 2016). "These SMs are largely located to EGF-like domains that may functionally compromise and increase HNSCC recurrence and fatality, suggesting that NOTCH1 performs a tumour suppressive role in HNSCC." (PMID 27035284, 2016).